IL22RA2 (interleukin 22 receptor subunit alpha 2)
Description:
Isoform 2 is a receptor for IL22. Binds to IL22, prevents interaction with the functional IL-22R complex and blocks the activity of IL22 (in vitro). May play an important role as an IL22 antagonist in the regulation of inflammatory responses. Isoform 1 may play a role in establishing and maintaining successful pregnancy.
Synonyms: IL-22R-alpha-2; IL-22RA2; CRF2-10; CRF2-S1; IL-22BP; CRF2X; ZCYTOR16
Tractability: Antibody: UniProt places it where antibodies can reach, with high confidence; its Gene Ontology location is reachable by antibodies, with high confidence; UniProt predicts a signal peptide or a membrane-spanning region.
Gene: Protein-coding gene on chromosome 6 (137,143,820 to 137,173,648, reverse strand). Ensembl gene ENSG00000164485.
Subcellular location: Secreted
Pathways (Reactome):
Immune System: Interleukin-20 family signaling
Gene Ontology:
Molecular function: interleukin-22 binding; interleukin-22 receptor activity; cytokine receptor activity
Biological process: cytokine-mediated signaling pathway; negative regulation of inflammatory response; interleukin-22-mediated signaling pathway
Cellular component: decoy receptor complex; extracellular region; plasma membrane; cytosol
Genetic constraint (gnomAD): Loss-of-function variants: 33 observed, 30.98 expected, observed/expected ratio (o/e) 1.07, 90% interval 0.81 to 1.42. The upper end of that interval is the gene's LOEUF score, 1.42, which puts it in group 5 of 6, group 1 being the genes least tolerant of losing a copy. Missense variants: 285 observed, 299.38 expected, observed/expected ratio (o/e) 0.95, 90% interval 0.86 to 1.05. Synonymous variants: 89 observed, 99.49 expected, observed/expected ratio (o/e) 0.89, 90% interval 0.75 to 1.07.
Homologues: Orthologues: chimpanzee IL22RA2 (98% identical), macaque IL22RA2 (84% identical), dog IL22RA2 (73% identical), pig IL22RA2 (70% identical), rat Il22ra2 (63% identical), rabbit IL22RA2 (61% identical), guinea pig IL22RA2 (61% identical), mouse Il22ra2 (58% identical). Paralogues in human: IL20RA (29% identical), IL22RA1 (24% identical), IL10RA (21% identical), IFNLR1 (20% identical), F3 (20% identical), IFNAR1 (19% identical), IL20RB (18% identical), IFNAR2 (17% identical), IL10RB (17% identical), IFNGR1 (17% identical), IFNGR2 (15% identical).
Diseases named in the same sentence as IL22RA2 in open-access papers:
IL22RA2 is named in the same sentence as 64 diseases in open-access papers, as found by Europe PMC text mining. Sharing a sentence is not in itself a finding about the gene and the disease. The quoted sentences say what the papers report.
colitis (12 papers, 2016 to 2023). Inflammation of the colon. "Using a novel humanized model of experimental colitis, we demonstrate that TNF interfered with the tissue repair program via induction of a soluble natural antagonist of IL-22 (IL-22Ra2; IL-22BP) in the colon and abrogated IL-22/STAT3-mediated mucosal repair during colitis." (PMID 35383266, 2022).
influenza infection (9 papers, 2020 to 2023). "Additionally, this group showed that Il22ra2-/- knockout mice had enhanced tight junctions during influenza infection promoting tissue integrity." (PMID 33968082, 2021).
Hepatic fibrosis (6 papers, 2016 to 2024). The presence of excessive fibrous connective tissue in the liver. "In contrast, studies identifying polymorphisms in the IL22RA2 gene were associated with hepatic fibrosis from schistosome or hepatitis C virus (HCV) infection." (PMID 34868019, 2021). "These genotypes were associated with higher levels of IL22RA2 transcripts, suggesting that IL-22BP aggravates liver fibrosis, although no mechanistic experiments were performed to support this hypothesis." (PMID 34868019, 2021).
acute pneumonia (3 papers, 2017 to 2024). "Specifically, this study showed that knocking out Il22ra2 reduces viral-induced pneumonia, suggesting the balance between IL-22 and IL-22BP is more complex than initially thought." (PMID 38101567, 2024).
cerebral malaria (2 papers, 2019 to 2021). A sequestration of Plasmodium falciparum in the brain, which can cause coma and/or seizures. "In 2017, another recent study on infectious disease (cerebral malaria, CM) that induced by Plasmodium falciparum assessed 47 SNPs of IL-22 and IL-22RA2 in children from Mali and Nigeria and revealed the involvement of IL-22 SNPs in the pathogenesis of CM." (PMID 31749919, 2019).
infectious colitis (2 papers, 2022 to 2023). A viral or bacterial infectious process affecting the large intestine. "We and others have shown that the expression of IL22RA2 is down-regulated during infectious colitis but not in IBD inflamed tissues, hence suggesting possible pathophysiological relevance for the IL-22BP-dependent modulation of IL-22 bioactivity." (PMID 36311796, 2022).
multiple sclerosis (2 papers, 2020 to 2024). A progressive autoimmune disorder affecting the central nervous system resulting in demyelination. "For instance, IL22RA2, is a multiple sclerosis risk gene and has been shown to play a role in oligodendrocytic apoptosis." (PMID 38995454, 2024). "The IL22RA2 locus is associated with risk for multiple sclerosis (MS) but causative variants are yet to be determined." (PMID 31936765, 2020).
acute respiratory distress syndrome (1 paper, 2024). Progressive and life-threatening pulmonary distress in the absence of an underlying pulmonary condition, usually following major trauma or surgery. "This study showed the necessity of IL-22BP in controlling and preventing acute lung injury using IL-22BP knockout mice (Il22ra2−/−) in the bleomycin model of acute lung injury/acute respiratory distress syndrome." (PMID 38101567, 2024).
Arthritis (1 paper, 2025). Inflammation of a joint. "The observed arthritis may potentially relate to PEX7 deletion, while deletions in IL20RA and IL22RA2 might exacerbate inflammatory dysregulation or skin eruption." (PMID 40859316, 2025).
breast carcinoma (1 paper, 2022). "IL22RA2 expression decreases in luminal A, B, and triple-negative breast cancers; however, but HER2+ breast cancer has not been reported." (PMID 36338974, 2022).
diabetes (1 paper, 2020). "Strikingly, we were able to show that diabetes-prone pre-implantation embryos from NOD mice differentially overexpressed some of the previously identified immune-related genes, such as Ifngr1 and Il22ra2." (PMID 32796510, 2020).
intestinal polyp (1 paper, 2023). Discrete abnormal tissue masses that protrude into the lumen of the intestine. "To identify Il22ra2-expressing cells in the intestine, we purified EpCAM+ epithelial cells and CD45+ leukocytes from intestinal polyps and found that Il22ra2 mRNA was expressed only in CD45+ but not in epithelial cells." (PMID 36932082, 2023).
intestinal tumors (1 paper, 2023). "Although we have only compared tumor development between Il22ra2–/– and Il22ra2+/+ mice on the Clec7a–/– background, these results suggest that enhanced expression of Il22ra2 in Clec7a–/– mice protects these mice from intestinal tumor development." (PMID 36932082, 2023). "Furthermore, Il22ra2 expression in intestinal tumors or IL-22BP expression in myeloid cells was suppressed by PGE2 treatment both in vivo and in vitro, suggesting that IL-22BP production is negatively regulated by PGE2." (PMID 36932082, 2023).
Oral ulcer (1 paper, 2023). Erosion of the mucous mebrane of the mouth with local excavation of the surface, resulting from the sloughing of inflammatory necrotic tissue. "Ultimately, we identified 6 potential risk genes (BTN3A3, IL12B, BPI, FAM213A, PLXNB2, and IL22RA2) of mouth ulcers with altered protein abundances in the blood." (PMID 37369724, 2023). "In conclusion, we found strong evidence supporting six novel blood proteins (BTN3A3, IL12B, BPI, FAM213A, PLXNB2, and IL22RA2) associated with mouth ulcers." (PMID 37369724, 2023). "Second, by using Bayesian colocalization, two correlated signals with common causal variants can be estimated at specific sites, and the causative proteins of oral ulcers (BTN3A3, IL12B, BPI, FAM213A, PLXNB2, and IL22RA2) were validated." (PMID 37369724, 2023). "Following this analysis, the researchers identified 6 key genes, namely BTN3A3, IL12B, BPI, FAM213A, PLXNB2, and IL22RA2, which were related to the onset of mouth ulcers." (PMID 37369724, 2023). "However, only six genes (BTN3A3, IL12B, BPI, FAM213A, PLXNB2, and IL22RA2) assembled the criterion (PPH4 > 75%) in the analysis of mouth ulcers, indicating a shared single variant with mouth ulcers." (PMID 37369724, 2023).
pneumococcal pneumonia (1 paper, 2023). A febrile disease caused by STREPTOCOCCUS PNEUMONIAE. "Consequently, IL-22 and IL-22BP coregulate antimicrobial immunity against S. pneumoniae, suggesting that IL-22RA2 may be an effective target for the treatment of pneumococcal pneumonia." (PMID 36839448, 2023).
polyp (1 paper, 2023). A usually exophytic mass attached to the underlying tissue by a broad base or a thin stalk. "Il22ra2 was exclusively detected in CD11b+ and CD11c+ myeloid cells, but not in Thy1.2+ T cells, CD19+ B cells or other CD45+ cells in both colonic polyp and non-polyp tissues, and its expression was mainly detected in CD11c+ DCs, but not in CD11c–CD11b+ or other myeloid cells." (PMID 36932082, 2023).
Psoriasiform dermatitis (1 paper, 2018). A skin abnormality characterized by redness and irritation, with thick, red skin that displays flaky, silver-white patches (scales). "The transcriptional expression of Il22ra2 was decreased during the development of psoriasiform dermatitis in ear skin and skin-draining PLNs." (PMID 29977242, 2018).
tumor (20 papers, 2020 to 2025). "We identified IL16 and IRF4 to be broadly downregulated in tumor-infiltrating DCs, CXCR4 to be broadly upregulated, and IL18 and IL22RA2 increases to be associated with cDC2s." (PMID 39932553, 2025). "If this is the case, then the effect of BRRF1 with the downregulated IL-22RA2 will amplify tumor progression induced by IL-22." (PMID 39769218, 2024). "In support for this notion, we showed that administrating Clec7a−/− mice with PGE2 suppressed colonic Il22ra2 expression and abrogated the tumor suppression in Clec7a−/− mice." (PMID 36932082, 2023). "On another note, IL-22RA2 has a regulatory role, as it is constitutively expressed in various tissues, but in cancer, it appears to be decreased, which can allow IL-22-induced tumor growth." (PMID 39769218, 2024). "Interestingly, we found that Il22ra2 expression in tumor-infiltrating cells was suppressed by PGE2 through the suppression of the expression of RA-synthase genes and may also through the induction of IL-18, an inhibitor of Il22ra induction." (PMID 36932082, 2023). "We extracted cells from the myeloid cluster of the tumor fraction; these cells were clustered in 10 myeloid cell types including, monocyte, macrophage-like, dendritic cells (DC) 1, DC2, DC2 C1Q+, DC IL22RA2, pDC, AS-DC, mregDC, and granulocyte." (PMID 38611120, 2024). "We found that the IL22RA2 mRNA was decreased, while PTGS2 mRNA was significantly increased in tumors compared with non-tumor tissues." (PMID 36932082, 2023). "A total of 30 IL22RA1-correlated genes (e.g. IL17D, IL22RA2, IL20RB, IL10RA, IL10RB, TSLP and TYK2) are involved in the JAK/STAT pathway which promotes tumor progression." (PMID 35874683, 2022). "By scRNA-seq analysis, we found a group of DCs, which we named tumor-associated DC (TADC) because this DC subset uniquely expresses tumor-associated genes such as Pclaf, Spc24 and Top2a, highly expressed Il22ra2 in Clec7a−/− mice but not in WT mice." (PMID 36932082, 2023).
infection (12 papers, 2015 to 2026). The state of being infected such as from the introduction of a foreign agent such as serum, vaccine, antigenic substance or organism. "During respiratory infection caused by Streptococcus pneumoniae, IL22RA2(−/−) mice were more resistant to contagion, had increased IL-22 levels in lung tissues, and sustained longer survival upon infection than control mice." (PMID 39195286, 2024). "In addition, mice deficient in IL-22RA2 (the gene encoding IL-22BP) showed reduced susceptibility to S. pneumoniae and prolonged survival after infection." (PMID 36839448, 2023). "Most of the genes for chemokines/chemokine receptors (CCR2, CCR6, CCR7, CSF2RB, CX3CR1 and CXCR4) and cytokines/cytokines receptors (IL1R2, IL8, IL18, IL20RA and IL22RA2) were down-regulated after infection by vvIBDV at 3 dpi." (PMID 33110122, 2020). "In the present study, mRNA coding for cytokines and cytokine receptors involved in the JAK-STAT pathway, including IL19, IL20, IL21R, and IL22RA2, were highly expressed in lower trachea during host-adapted swH1N1 infection compared to non-adapted huH1N1 infection." (PMID 39247193, 2024).
cancer (6 papers, 2018 to 2024). A tumor composed of atypical neoplastic, often pleomorphic cells that invade other tissues. "The human IL22RA2 gene locus contains single nucleotide polymorphisms (SNPs) that are associated with cancer remission and risk to contract multiple sclerosis (MS)." (PMID 30619294, 2018). "IL-22, IL-22R, and IL-22RA2 interactions play an important role in health and diseases and are involved in regulating cancer and homeostasis." (PMID 39769218, 2024). "However, in cancer, IL-22RA2 was found to be decreased, which would then allow IL-22 tumorigenic effects." (PMID 39769218, 2024).
colonic polyps (2 papers, 2023 to 2025). "Interestingly, we noticed that COX2 mRNA levels were negatively correlated with the Il22ra2 expression in colonic polyps under both GF and SPF conditions." (PMID 36932082, 2023).
immune disorders (1 paper, 2023). "The most highly upregulated gene was IL22A2, and IL22RA2, which regulates shared central pathways, and is a common risk gene for several immune disorders." (PMID 36670847, 2023).
IL22RA2 also shares sentences with these, for which no sentence is quoted: psoriasis (11 papers); inflammatory bowel disease (10); colon carcinoma (5); colorectal cancer (4); atopic dermatitis (3); COVID-19 (3); autoimmune disease (2); Chronic colitis (2); Crohn disease (2); infectious disease (2); inflammation (2); African trypanosomiasis (1); asthma (1); atherosclerosis (1); bacterial pneumonia (1); Cirrhosis (1); co-infection (1); cognitive deficits (1); colon adenocarcinoma (1); colorectal tumor (1); Hepatitis C (1); Hypertension (1); injury (1); intestinal inflammation (1); liver cancer (1); liver diseases (1); lung carcinoma (1); Lymph node metastasis (1); memory impairment (1); metastatic tumor (1).
A further 12 diseases each share a sentence with IL22RA2 in 1 paper.